YAP1 (Yes1 associated transcriptional regulator)
Diseases named in the same sentence as YAP1 in open-access papers (continued):
Sharing a sentence is not in itself a finding about the gene and the disease.
tumor (continued). "Overall, these results establish that YAP1 is a direct oncogenic target of the 11q22 amplicon in previously unreported cancer types and support the relevance of such genetic aberration in carcinogenesis in a fraction of multiple tumor types." (PMID 24810989, 2014). "Furthermore, genomic amplification events of 11q22 locus encompassing YAP1 gene have been detected in multiple tumor types but there is limited direct evidence about the oncogenic role of endogenous YAP1 within in the amplicon." (PMID 24810989, 2014). "Red/green assays with shYAP1-GFP+ CC14 cells injected subcutaneously into nude mice revealed that YAP1 is cell autonomously essential for tumor growth as green cells disappeared from the tumor, again showing the opposite phenotype of shTMED3- and shSOX12-expressing cells." (PMID 24920608, 2014). "Furthermore, downregulation of YAP1 was shown to increase anoikis, migration and invasion, altogether suggesting a tumour suppressive function for YAP1." (PMID 24559095, 2014). "Furthermore, the 11q22 genomic region was found amplified in individual cases of several human tumor types but the direct evidence of YAP1 amplification is described in very few of these cases." (PMID 24810989, 2014). "Indeed, these genes represent YAP1 targets modulated in multiple different normal and tumor cell contexts." (PMID 24810989, 2014). "Yes-associated protein 1 gene (YAP1) located at 11q22, a site of frequent loss of heterozygosity in sporadic BC have been indicated that may act as a tumor suppressor." (PMID 24223879, 2013). "In addition to the interaction with P73-driven tumor suppression pathway, present study had found that YAP1 displayed as a protein that integrate another RASSF1A-driven tumor suppressor pathway with the P73 pathway." (PMID 24223879, 2013). "But more importantly, the difference in YAP1 protein level between tumor and adjacent normal epithelium is much more significant in the nucleus (p-value = 0.0007) than in the cytoplasm (p-value = 0.027), indicating that YAP1 is not only overexpressed in PDA but it is also highly activated." (PMID 22396793, 2012). "Although the oncogenic activity of YAP1 has been clearly demonstrated, data from some studies also indicate that YAP1 might be tumor suppressive in certain cell types." (PMID 22396793, 2012). "In human cancer, the YAP1 gene was reported as amplified and over-expressed in several tumor types." (PMID 22396793, 2012). "When we evaluated the correlation between nuclear localization of YAP1 and tumor grade, nuclear localization of YAP1 was preferentially detected in high-grade, suggesting that the suppression of Hippo signaling through SAV1 downregulation tends to occur in high-grade ccRCCs." (PMID 22185343, 2011). "Molecular profiling of transformed and metastatic murine SCCs showed that Gro1 (IL8 homolog), antiapoptotic gene cIAP-1 (cIap-1/Birc2), and Yap65 (YAP 1) were upregulated and clustered together in association with activation of NF-κB and tumor growth, metastatic progression, and angiogenesis." (PMID 17498291, 2007). "Furthermore, in a UTUC patient-derived organoid model, high expression levels of RRBP1 have been associated with chemoresistance to cisplatin, gemcitabine and epirubicin; therefore, it synergistically promotes tumor cell survival by modulating ERS and yes-associated protein 1 (YAP1) signaling." (PMID 41200062, 2026). "Interestingly, YAP1 has been identified as a tumour suppressor gene in haematological cancers, where it is preferentially inactivated, suggesting that restoring YAP1 function could represent a novel therapeutic strategy." (PMID 40387441, 2025). "TGFβ3/GLI2/YAP1 expression was associated with anti-tumor immune desertion, as evident by a negative association with tumor-infiltrating lymphocytes, including the CD8 T cells, CD4 T cells, B cells, Th1, gamma delta T cells (γδ T cells), and T follicular helper cells (Tfh)." (PMID 40027190, 2025).
tumor (continued). "Notably, hyperactivation of YAP1 in CAFs enhances tumor cell adhesion to CAFs via N-cadherin." (PMID 40399946, 2025). "To further explore whether targeting the NAT10/XIST/YAP1 axis augments the antitumor effect of immune checkpoint inhibitors (ICIs), we administered Remodelin, Verteporfin, and an anti-PD-1 monoclonal antibody to tumor-bearing mice." (PMID 40860183, 2025). "Additionally, YAP1-driven transcriptional responses may enable tumor cells to adapt to chemotherapy-induced stress, particularly in the neoadjuvant context." (PMID 40731926, 2025). "Moreover, miR-34a and miR-605-5p may function as tumor-suppressive miRNAs in MCF-7 cells by reducing YAP1 expression." (PMID 39345743, 2024). "Hence, upregulation of YAP1 might enhance the response to immunotherapy by inhibiting Treg cell infiltration into the tumor microenvironment." (PMID 38515849, 2024). "The transcriptional co-activators Yes1-associated protein (YAP1) and WW domain-containing transcription regulator protein 1 (WWTR1, also known as TAZ) are fundamentally important regulators of stem cell proliferation, tissue regeneration, and tumor formation in mammalian epithelia." (PMID 38540020, 2024). "Additionally, in gastric cancer, RP11-323N12.5 upregulates tumor growth by promoting YAP1, and higher expression of RP11-323N12.5 is detected in tumor-infiltrating leucocytes (TILs), which might be generated from SEVs and is also linked to tumor progression." (PMID 38243280, 2024). "Consequently, we posit that PRRG2 could potentially impede tumor proliferation and metastasis through the activation of the Hippo signaling cascade, thereby inhibiting YAP1 activity." (PMID 38227081, 2024). "Indeed, TME subtypes exhibiting fibrosis or a mesenchymal subtype despite high immune infiltrate are unresponsive to pembrolizumab, suggesting that therapeutic targeting the Hippo/Yap1 or STAT3 pathways could potentially enhance anti-tumor immune responses." (PMID 37957015, 2024). "This study revealed that PUFAs-enriched OCM/AS of EOC promotes M2-like TAM polarization through RhoA-YAP1 inhibition, where YAP1 downregulation is required for accelerating protumoral M2-like TAM polarization, thereby causing immunosuppression and enhancing tumor progression." (PMID 39198883, 2024). "Therefore, to determine whether UPS cell–intrinsic Yap1 modulates T cell effector function in addition to inhibitory receptor expression, we treated tumor-bearing KP and KPY mice with anti-Pd1 or isotype control antibody." (PMID 38652549, 2024). "However, molecular mechanisms underlying the functional connection between YAP1 activity and the tumor-promoting functions of CAFs have not been fully identified." (PMID 38308096, 2024). "Although our analysis of Gp130FF; Yap1KO mice clearly shows that tumor cell–intrinsic Yap1 expression impacts tumor burden, it remains unclear whether this is a direct effect reducing tumor growth or indirect effect arising from enhanced anti-tumor immune activity." (PMID 37957015, 2024). "Finally, we assessed whether Yap1-depletion in Yap1KD; Gp130FF tumor organoids reduced expression of gp130 cytokines and found that indeed this effect was more pronounced on IL11 than IL6." (PMID 37957015, 2024). "Therefore, we speculate that TPM2 inhibits tumor development by inhibiting the nuclear localization of YAP1, which is common to other cancer types." (PMID 36823643, 2023). "Moreover, they have also highlighted that the hyperactivity of YAP1 was highly related to the increased tumor stage and poor prognosis in ERMS and FN-ARMS (FN-RMS) and the knockdown of YAP1 could reduce ERMS (FN-RMS) tumorigenicity." (PMID 36793601, 2023). "These tumors displayed the expression of the biliary fate determinants Sox9 and Yap1 and interestingly, conditional deletion of each of these genes separately significantly reduced the burden of iCCA, while combined deletion of both genes completely abolished tumor formation." (PMID 36609378, 2023).
tumor (continued). "USP10 decreases ubiquitin-mediated degradation of YAP1 and further elevates cysteine-rich 61 (Cyr61), which then restores programmed cell death 1 ligand 1 (PD-L1) and galectin-9 expression and stimulates M2 polarization, thereby helping tumor cells evade from immune surveillance." (PMID 38174069, 2023). "Moreover, PA treatment markedly increased the tumor-killing ability of wild-type but not Yap1;Taz-deficient neutrophils." (PMID 36921037, 2023). "Yes-Associated Protein 1 (YAP1) is a transcriptional coactivator, which upon binding to many transcription factors, such as TEAD3 (Transcriptional Enhanced Associate Domain 3), regulates the Hippo-signalling pathway, contributing to tumor growth, and resistance." (PMID 37055532, 2023). "Among the altered genes, BNC2 is a putative tumor suppressor; RASA1 gene (Ras p21 protein activator 1) is the regulator of Ras oncogene, and mutation in RASA1 may turn on oncogenic pathways; Smad2 is a tumor suppressor; and Yap1 is an oncogenic co-activator in the Hippo pathway when overexpressed." (PMID 36865791, 2023). "We could not analyze the association between YAP1, tumor stiffness, and clinical implication because of different patient cohorts." (PMID 37894401, 2023). "Although both our current work and previous study have shown that SRC kinase could inhibit the Hippo tumor suppressor pathway through tyrosine phosphorylation of LATS1 in a YAP1-dependent manner, we still observed the increased TEAD-associated transcriptional activity in LATS1/2 knockdown cells." (PMID 36633714, 2023). "Furthermore, WWP2 silencing attenuated tumor growth by regulating the Hippo-YAP1 pathway in vivo." (PMID 36803368, 2023). "It was shown that YAP1 silencing in tumor stromal cells could inhibit PCa growth." (PMID 36899938, 2023). "Therefore, we presume that YAP1‐1 might act as the dominant isoform in tumours with low malignancy, while YAP1‐2 might act more important in tumours with high malignancy." (PMID 35014181, 2022). "In addition, silencing YAP1 in tumor stromal cells can inhibit tumor growth in PCa." (PMID 36139572, 2022). "To identify candidate downstream genes of YAP1 in FN‐RMS, we interrogated published transcriptome data obtained from tumor‐derived cell lines originating from a conditional genetically engineered mouse model in which YAP1 could be turned on or off to grow or shrink FN‐RMS tumors." (PMID 36037042, 2022). "Though expression of YAP1 by tumor cells propagates tumor growth, recent research has shown that there are binary pan-cancer classes where YAP1 displays either pro- or anti-cancer activity depending on whether it is expressed or silenced in different types of cancer." (PMID 35189960, 2022). "In that study, we used a tissue microarray (TMA) sample, which was one of the major limitations of that study because nuclear YAP1 expression was only focally present in the tumor; thus, YAP1 expression in the cancer tissue of a 3 mm-sized TMA core might not be representative." (PMID 36291755, 2022). "Furthermore, the Hippo pathway could suppress the growth and tumor formation of HCC by inhibiting YAP1 and thereby downregulating TAMs in the microenvironment." (PMID 35672802, 2022). "Also, tumors with non-collagen-type stroma showed an association between YAP1 expression and tumor stiffness." (PMID 36291755, 2022). "Furthermore, in 3D tumor spheroid invasion assays, we observed that YAP1 overexpression induced the formation of pseudopod-like structures on the rim of MCF7 cell spheres, whereas YAP1 knockdown significantly inhibited MDA-MB-231 cell growth and invasiveness in the 3D culture environment." (PMID 35773411, 2022). "Next, we examined whether YAP1-induced invadopodia formation and promoted tumor metastasis in vivo." (PMID 35773411, 2022). "Furthermore, the inhibitory effect of SNHG16 on tumor growth was rescued by YAP1 overexpression." (PMID 36147462, 2022).
tumor (continued). "Finally, to explore whether wogonin decreased YAP1 expression in vivo, we constructed a subcutaneous transplantation tumor model in BALB/c nude mice." (PMID 35037825, 2022). "Thus, we performed a co-transfection assay to further explore whether YAP1 is also involved in miR-335-induced inhibition of tumor growth and metastasis, as is KDM3A." (PMID 33888871, 2022). "In addition, we observed increased tumor progression in the Lv-Oe-YAP1 group." (PMID 36147462, 2022). "Therefore, silencing YAP1 in tumor stromal cells can effectively inhibit tumor growth." (PMID 36139572, 2022). "Thus, pharmacological or genetic inhibition of YAP1 can inhibit tumor progression." (PMID 34974798, 2022). "Notably, we demonstrated that treatment of primary fibroblasts with FAPα/EBV-LMP1-containing exosomes derived from NPC cells activated fibroblasts by stimulating the functions of YAP1 and FAPα, thereby enhancing fibrotic responses and tumor growth in mouse xenografts." (PMID 35986369, 2022). "Therefore, SNHG16 and YAP1 form a positive feedback loop to regulate tumor progression." (PMID 36147462, 2022). "Similarly, miR-132 could lead to tumor regression of HCC by targeting YAP1 and suppressing the expression of YAP1." (PMID 35672802, 2022). "Furthermore, 8.6% of OSCC primary tumours show an amplification of the YAP1 locus and 21.6% with truncated FAT1, an upstream membrane receptor protein in the Hippo kinase cascade, which results in increased YAP1 activity, malignant progression and poor patient prognosis." (PMID 34680271, 2021). "However, when the tumors progress to a higher degree of malignancy after undergoing EMT, YAP1-2 becomes preferentially stabilized, leading to increased nuclear localization and interactions with additional nuclear factors to promote tumor invasion and metastasis." (PMID 34094936, 2021). "Similarly, the only tumour with a YAP1+ signature exhibited the YAP1‐MAMLD1 fusion." (PMID 34314101, 2021). "Though YAP1 is assumed to act as an oncoprotein, an increasing number of studies have reported that YAP1 may have tumor-suppressor and pro-apoptotic functions, suggesting a paradoxical role of YAP1, probably dependent on the cellular context and binding partners." (PMID 33670622, 2021). "Therefore, we speculated that PWAR6 exerts its tumour suppressive role by negatively regulating YAP1." (PMID 33834618, 2021). "However, the underlying mechanisms by which YAP1 contributes to tumor immunity is not clearly established." (PMID 34150844, 2021). "Moreover, the translocation pattern was categorized using “site-index”, and the results demonstrated that the overexpression of HMGB1 and SOX9 was mostly observed in both the nucleus and cytoplasm, whereas YAP1 was predominantly expressed in the cytoplasm of tumor cells." (PMID 35201494, 2021). "Therefore, our study reveals that the lncRNA HPR, which shows high tumour expression, may play a role in tumour growth by co-regulating mTORC1 and YAP1 activation." (PMID 34462427, 2021). "Therefore, interactions between LATS2 and YAP1 may be a potential mechanism for regulation of the tumor microenvironment in CRC, although further studies are necessary to confirm this hypothesis." (PMID 34699318, 2021). "Notably, the expression of YAP1 was significantly increased with tumor grade from well to poor." (PMID 33495462, 2021). "Interestingly, a subset of tumor cells was able to restore Myc levels allowing cell survival through the induction of genes encoding EMT-TFs Snail, Zeb2, Twist2, and the stemness factor Sox2, thus compensating for Yap1 loss." (PMID 34888306, 2021). "In addition, breast cancer cell-secreted miR-205 contributes to the conversion of breast NFs into CAFs by promoting YAP1 expression and subsequent tumour angiogenesis, and activates Myc signalling in CAFs to induce an optimal metabolic environment for sustained tumour growth." (PMID 33477629, 2021).
tumor (continued). "Therefore, we demonstrated that circRNA_100876 over-expression in GC could promote GC tumor growth, migration and invasion and exert its effects through miR-665/YAP1 signaling." (PMID 33262782, 2020). "IMUP may promote progression of PTC tumour cells via the Hippo‐YAP1 pathway." (PMID 33094920, 2020). "Finally, tumor-promoting effect of MIR4435-2HG could be inhibited by the knockdown of YAP1 expression." (PMID 32154166, 2020). "Moreover, LINC00152 is required for YAP1‐induced cell proliferation and tumor growth of CRC." (PMID 32042551, 2020). "Additionally, the quantity of nuclear DUSP10 in CRC tumor biopsies is directly correlated with high tumor stage CRC and poor prognosis and survival in a large cohort of CRC patients, being also associated to high expression of nuclear YAP1." (PMID 32410997, 2020). "Analysis of tumor lysates from control and metformin-treated mice showed an obvious increase in expression of phosphorylated AMPKa proteins; and there was a significant decrease in Yap1, CCNE1 and CCNE2 protein levels in tumors from mice treated with metformin." (PMID 31455378, 2019). "Moreover, compared with scrambled shRNA, YAP1 knockdown significantly decreased the tumor weights." (PMID 29700328, 2018). "Finally, we show that targeting unrestrained YAP1 may represent an attractive precision therapeutic option for cancers harboring genomic alterations in the FAT1 tumor suppressor genes." (PMID 29985391, 2018). "Therefore, we suggest that PD-L1 immunotherapy, singly or in combination with a YAP1 inhibitor, may not only reduce tumor aggressiveness but it could also overcome TKI resistance in NSCLC, particularly in patients with tumors that express both PD-L1 and YAP1." (PMID 29435131, 2018). "Thus, inhibiting Yes and the subsequent transcriptional activity of YAP1 had a substantial anti-tumor cell effect both in vitro and in vivo and may provide a viable therapeutic approach for patients with NF2-deficient PRCC." (PMID 29535838, 2018). "Hence, inhibition of YAP1 expression may prevent tumor progression and improve prognosis in various malignancies, including GC." (PMID 29296196, 2017). "Then, we further discovered that IKBKE increased Yes-associated protein 1 (YAP1) and TEA domain family member 2 (TEAD2), two important Hippo pathway downstream factors, to induce an epithelial–mesenchymal transition (EMT), thus contributing to tumour invasion and metastasis." (PMID 28548934, 2017). "Therefore, agents that target and suppress the expression of YAP1-mediated signaling may act as a dual anti-cancer agent by disrupting the molecular connections between TAMs and tumor cells." (PMID 28241877, 2017). "Thus, the tumor-related functions of YAP1 may depend on different upstream activators and/or transcriptional co-factors resulting in the activation of distinct target genes." (PMID 29179447, 2017). "Another mechanism is probably responsible for the apparent increase in the expression of YAP1 protein: a higher concentration of oxygen in cell culture than in the tumor bulk in vivo may induce the overexpression of proteins involved in the response to oxidative stress." (PMID 28231263, 2017). "Regulation of the transcriptional co-activators Yes-Associated Protein 1 (YAP1) and transcriptional coactivator with PDZ-binding motif (TAZ) is a key output of the Hippo signaling pathway in control of cell proliferation, tissue repair and in tumor progression (reviewed in reference 1)." (PMID 27462448, 2016). "Notably, YAP-1 signalling preserved expression of both integrin beta-1 and ITGA11 implying auto-regulation similarly to YAP-1’s function in cancer-associated fibroblasts, where MYL9 was a key regulator of the ECM and tumour invasion." (PMID 27535340, 2016).